PDZRN4 (PDZ domain containing ring finger 4)
Synonyms: LNX4; DKFZp434B0417; FLJ33777; IMAGE5767589; SAMCAP3L
Tractability: No criterion of Open Targets' tractability assessment is met for any kind of drug.
Gene: Protein-coding gene on chromosome 12 (41,188,320 to 41,574,745, forward strand). Ensembl gene ENSG00000165966.
Subcellular location (Human Protein Atlas): Mitochondria
Gene Ontology:
Molecular function: protein binding
Genetic constraint (gnomAD): Loss-of-function variants: 50 observed, 70.79 expected, observed/expected ratio (o/e) 0.71, 90% interval 0.56 to 0.89. The upper end of that interval is the gene's LOEUF score, 0.89, which puts it in group 3 of 6, group 1 being the genes least tolerant of losing a copy. Missense variants: 1,262 observed, 1,135 expected, observed/expected ratio (o/e) 1.11, 90% interval 1.06 to 1.16. Synonymous variants: 474 observed, 420.83 expected, observed/expected ratio (o/e) 1.13, 90% interval 1.04 to 1.22.
Homologues: Orthologues: chimpanzee PDZRN4 (99% identical), macaque PDZRN4 (97% identical), pig PDZRN4 (90% identical), mouse Pdzrn4 (79% identical), dog PDZRN4 (67% identical), guinea pig PDZRN4 (67% identical), rat Pdzrn4 (65% identical), tropical clawed frog pdzrn4 (58% identical), rabbit PDZRN4 (55% identical), zebrafish pdzrn4 (41% identical), Drosophila melanogaster Slip1 (19% identical), Caenorhabditis elegans C50F7.6 (12% identical). Paralogues in human: PDZRN3 (58% identical), PDZD4 (36% identical).
Diseases named in the same sentence as PDZRN4 in open-access papers:
PDZRN4 is named in the same sentence as 15 diseases in open-access papers, as found by Europe PMC text mining. Sharing a sentence is not in itself a finding about the gene and the disease. The quoted sentences say what the papers report.
multiple sclerosis (2 papers, 2020 to 2022). A progressive autoimmune disorder affecting the central nervous system resulting in demyelination. "PDZ domain-containing ring finger 4 (PDZRN4) is located on chromosome 12q12 and encodes the PDZ domain-containing ring finger 4 (PDZRN4), which belongs to the LNX family and acts as a suppressor in multiple cancers and in association with multiple sclerosis in a GWAS." (PMID 36704746, 2022).
prostate carcinoma (2 papers, 2022 to 2024). A carcinoma that arises from epithelial cells of the prostate gland. "PDZRN4 is a functional suppressor of prostate cancer growth and development and a potential target of biochemical therapy in hormone-resistant PC." (PMID 35517421, 2022). "To explore the expression of PDZRN4 in prostate cancer samples, we analysed TCGA data and found that PDZRN4 was negatively correlated with the development of PC." (PMID 35517421, 2022). "To detect the expression of PDZRN4 in prostate cancer tissues, we explored several datasets in the TCGA system." (PMID 35517421, 2022). "We also found that the levels of PDZRN4 were decreased in prostate cancer, especially in CRPC tissues." (PMID 35517421, 2022). "There are few studies on the role of PDZRN4 in the pathogenesis of prostate cancer (PCa)." (PMID 35517421, 2022). "Nevertheless, there are few studies on the role of PDZRN4 in prostate cancer." (PMID 35517421, 2022).
Obesity (1 paper, 2019). Accumulation of substantial excess body fat. "Additionally, EXT1 at 8q24.11 is associated with obesity and PDZRN4 at 12q12 is associated with BMI and skin pigmentation." (PMID 30946739, 2019).
tumor (8 papers, 2017 to 2024). "After 4 weeks of growth, the tumour weights in mice injected with PDZRN4-kd LNCap and PC3 cells were significantly higher than those of in mice injected with control cells." (PMID 35517421, 2022). "In particular, the size of PDZRN4-kd tumours was dramatically larger than that of control tumours." (PMID 35517421, 2022). "PDZRN4 is described as a potential tumor suppressor with down-regulation in HCC." (PMID 28350845, 2017). "However, when LNCap cells were cultured in charcoal media, PDZRN4 knockdown failed to activate tumour growth." (PMID 35517421, 2022).
cancer (5 papers, 2019 to 2024). A tumor composed of atypical neoplastic, often pleomorphic cells that invade other tissues. "Pdzrn4 has limited association with cancer although according to the COSMIC database mutations have been found in 0.4% of hematological malignancies." (PMID 31013298, 2019). "In this study, we demonstrate that PDZRN4, acting as a cancer-suppressing gene, reduces the proliferation, invasion and migration capacities of PC cells regulated by androgen activation." (PMID 35517421, 2022). "Three in four PDZRN4 mutations were observed only in BM and not previously observed in the COSMIC database, while a nonsense mutation (p.R965*) showed an elevated cancer cell fraction in BM tissues (100% vs. 43%)." (PMID 31320627, 2019).
PDZRN4 also shares sentences with these, for which no sentence is quoted: breast carcinoma (2 papers); autism spectrum disorder (1); bipolar disorder (1); depression (1); hematological malignancies (1); hepatocellular carcinoma (1); papillary thyroid carcinoma (1); rectal adenocarcinoma (1); rectal cancer (1); schizophrenia (1).